USP48 (ubiquitin specific peptidase 48)
Diseases named in the same sentence as USP48 in open-access papers (continued):
Sharing a sentence is not in itself a finding about the gene and the disease.
tumor (20 papers, 2011 to 2025). "Mutations in genes encoding protein deubiquitinases USP8 and USP48 were determined in tumor tissue in the entire cohort of patients." (PMID 37065760, 2023). "Approximately 40% of patients have mutations in USP8 or USP48 genes that have a strong effect on tumor biology, including changes in the expression of cell cycle-related genes." (PMID 36428684, 2022). "However, further studies are needed to fully elucidate the clinical implications of USP48 mutations, including their potential role in predicting treatment response or tumor recurrence." (PMID 40364036, 2025). "Furthermore, it was found that tumors harboring USP48 mutations were associated with a smaller tumor size, often presenting as microadenomas." (PMID 40364036, 2025). "Thus, we explored whether patients with BRAF V600E or USP48-mutated tumor display distinct clinical features." (PMID 30093687, 2018). "USP48 mutations are found in a subset of USP8-wild-type tumors and are associated with a smaller tumor size and preserved feedback responsiveness to suppressive factors, but their clinical implications are still unclear." (PMID 40364036, 2025). "Collectively, the available data suggest that USP48 mutations contribute to CD’s pathogenesis and are a common mutation in USP8-wild-type CD, associated with a smaller tumor size and a tendency towards the female gender." (PMID 40364036, 2025). "MiR-489-3p promotes cell proliferation, migration, EMT, and tumor formation and metastasis by regulating USP48 and inactivating the Wnt/β-catenin pathway in non-small cell lung cancer." (PMID 40858914, 2025). "Because USP48 mutations affect the processes of protein degradation similarly to mutations of USP8, we screened the tumor samples for both the mutations." (PMID 33498176, 2021). "USP48 facilitates pyroptosis by binding with GSDME, stripping its K48-linked ubiquitin, and thereby augmenting the functions of T cells and tumor-associated macrophages (TAMs) within the tumor microenvironment (TME), significantly boosting the efficacy of PD-1 inhibitors." (PMID 38702734, 2024). "The Dub USP48 promotes pyroptosis and enhances anti-tumor immunity by stabilizing GSDME." (PMID 38584157, 2024). "The expression levels of four genes related to cell-cycle regulation were determined with qRT-PCR in tumor tissue from 70 patients with corticotroph tumors including patients with USP8 mutations (n = 20), USP48 mutations (n = 5) and wild-type patients (n = 42)." (PMID 36428684, 2022). "Additionally, METTL14-mediated m6A modification maintains sirtuin 6 (SIRT6) stability by regulating the expression of ubiquitin-specific peptidase 48 (USP48) and promoting the tumor suppressive function of glycolysis to regulate the metabolic activity of HCC." (PMID 36120301, 2022). "Gain-of-function mutations of ubiquitin-specific protease (USP) 8, USP48, and BRAF genes may subsequently cause overexpression of epithelial growth factor receptor (EGFR), and enhance POMC transcription, cell proliferation, and tumor growth." (PMID 33986726, 2021). "However, in contrast to 53BP1 loss, which can restore HR repair to BRCA1-deficient tumors, USP48 loss is not an expected mechanism of tumor resistance in BRCA1 patients as hyper-resection following USP48 loss requires BRCA1 function." (PMID 29335415, 2018). "Patients with BRAF V600E had significantly higher levels of midnight plasma ACTH (P = 0.023, Mann–Whitney U-test) and midnight serum cortisol (P = 0.007, Mann–Whitney U-test), but similar tumor sizes, when compared with patients carrying wild-type BRAF/USP48." (PMID 30093687, 2018).
tumor (continued). "On the other side, however, they are surely less prevalent than those found in the deubiquitinases USP8 and USP48, thus suggesting a more likely contribution in the modulation of tumor phenotype rather than in the transformation and/or progression." (PMID 35742910, 2022). "Tumor genetic defects in USP8, GNAS, USP48 and BRAF are some of the commonly encountered tissue-specific changes and may explain a larger percentage of the developed tumors." (PMID 31877737, 2019). "USP48 expression did not correlate with any clinico-pathological parameters since low levels of transcript were detected in almost all tumor samples (>95%, data not shown)." (PMID 21283576, 2011). "However, neither the genes encoding AURKA and USP8 nor those encoding USP48, BRAF, BRG1 and CABLES were affected in this tumor." (PMID 35563252, 2022). "Investigated molecules without connection to common key tumor proteins are GNAS, USP8, USP48, HHIPL1, NNAT, RHOU, C5orf66 and RASSF3, which seem to be more specific biomarkers and therefore should be validated for concordant differences in liquid biopsies." (PMID 32498309, 2020).
cancer (16 papers, 2011 to 2025). A tumor composed of atypical neoplastic, often pleomorphic cells that invade other tissues. "USP48 promotes pyroptosis in cancer cells by removing K48-linked ubiquitination at positions K120 and K189 of the GSDME." (PMID 38245760, 2024). "A CRISPR-Cas9 screen approach for identifying regulators of pyroptosis in cancer revealed that loss of USP48, a deubiquitinating enzyme, remarkably suppressed cell pyroptosis." (PMID 39075259, 2024). "Indicating that USP48 activation to be a sufficient strategy to sensitize cancer cells to pyroptosis and elevates response to immunotherapy." (PMID 39075259, 2024). "Mechanistically, USP18 inhibits pyroptosis in cancer cells via enhancing ISGs, while USP48 promotes pyroptosis by stabilizing gasdermin E (GSDEM)." (PMID 39048965, 2024). "The deubiquitination of SIRT6 by USP10 and USP48 inhibits cancer formation by preventing the growth and development of cancer cells." (PMID 37175631, 2023). "Data on the function of USP48 beyond cancer and its physiological role in other organs is still very scarce." (PMID 36293380, 2022). "Additionally, the mRNA expression of Aurora B was previously reported to be high in several cancers which also positively correlated with the expression levels of USP48, across a wide panel of cancer cells." (PMID 34445214, 2021). "Given that USP48 and Aurora B mRNA expression levels were positively correlated in cancer cells, we investigated whether the knockout of USP48 could affect the functions of Aurora B during the cell cycle." (PMID 34445214, 2021). "We observed significantly enhanced Mdm2 expression in the cancer cells with down-regulated USP48 levels, suggesting that USP48 could contribute to the regulation of Mdm2 expression in human cells." (PMID 28233861, 2017). "We observed that the high scores for USP48 mRNA expressions were directly proportional to the scores for Aurora B mRNA expression, suggesting a significant positive correlation between USP48 and Aurora B mRNA for all the cancer cell lines tested (n = 455, p < 0.0001; r = 0.3807)." (PMID 34445214, 2021). "According to recent literature, several DUBs were reported to regulate pyroptosis in cancer, including USP18, USP24, and USP48." (PMID 39048965, 2024). "An in vivo study indicates that upregulating USP48 can enhance the antitumor activity of PD-1 inhibitor, suggesting that USP48 activation pharmacologically could be a promising approach to enhance cancer cell sensitivity to pyroptosis and improve immunotherapy outcomes." (PMID 39048965, 2024). "Interestingly, in previous reports using cancer models and replicative cells, USP48 was usually localised at the cell nucleus but it may have a more subtle subcellular localisation in differentiated neurons, localising to synaptic sites and perinuclear cytosol." (PMID 36293380, 2022).
infection (1 paper, 2025). The state of being infected such as from the introduction of a foreign agent such as serum, vaccine, antigenic substance or organism. "First data in a proteome analysis from S. aureus infected macrophage-like cell line THP1 showed a decrease in the abundance of the analyzed proteins USP7, USP48, UCHL3, OTUD7B, and SENP1 (data not shown) which might indicate an intracellular role of Spls during infection." (PMID 39985644, 2025).
USP48 also shares sentences with these, for which no sentence is quoted: breast carcinoma (1 paper); cervical squamous cell carcinoma (1); colorectal cancer (1); deafness (1); External ophthalmoplegia (1); Fanconi anemia (1); lung adenocarcinoma (1); malaria (1); muscular dystrophy (1); non-small cell lung carcinoma (1); osteosarcoma (1); pituitary tumor (1); prostate adenocarcinoma (1); Retinal dystrophy (1).